SNORD114-12 (small nucleolar RNA, C/D box 114-12)
Synonyms: 14q(II-12)
Gene: Small nucleolar RNA gene on chromosome 14 (100,968,948 to 100,969,022, forward strand). Ensembl gene ENSG00000202270.
Gene Ontology:
Biological process: RNA processing
Cellular component: nucleolus
Homologues: Orthologues: chimpanzee SNORD114-12 (100% identical), macaque SNORD114-12 (96% identical). Paralogues in human: SNORD114-14 (92% identical), SNORD114-3 (85% identical), SNORD114-17 (83% identical), SNORD114-19 (81% identical), SNORD114-9 (81% identical), SNORD114-15 (80% identical), SNORD114-21 (80% identical), SNORD114-23 (80% identical), SNORD114-22 (77% identical), SNORD114-25 (77% identical), SNORD114-26 (76% identical), SNORD114-28 (76% identical), and 26 more.